INS (insulin)
Diseases named in the same sentence as INS in open-access papers (continued):
Sharing a sentence is not in itself a finding about the gene and the disease.
metabolic syndrome (continued). "Besides increased FBG and fasting insulin, IR has been also proved to be characterized as dyslipidemia (especially increased fasting TG and decreased HDL-C), and visceral obesity." (PMID 34537077, 2021). "Our result showed that papain enhanced the expression of AMPK in vivo and in vitro; these findings suggest implications in the insulin sensitivity and provide insights into whether the use of papain could be expanded to metabolic syndrome." (PMID 34576066, 2021). "FMT from lean donors has been implanted to obese subjects, after which metabolic syndrome and insulin sensitivity were improved by FMT, suggesting modulation of gut microbiome could be considered as a novel therapeutic target for the treatment of IR." (PMID 34884651, 2021). "Interestingly, in an intervention study of fecal microbiota transplantation from lean donors to men with metabolic syndrome, higher baseline S. variabile abundance was predictive of greater improvements in insulin sensitivity." (PMID 34579125, 2021). "The insulin concentrations in the CCL4 inhibition group were increased at 15 minutes but were significantly lower at 30 minutes compared to those in the untreated metabolic syndrome group during the OGTT." (PMID 33968046, 2021). "A recent study revealed that a low dose of metformin (10 mg/kg) mimics the effect of caloric restriction in mice, improving insulin sensitivity with aging and preventing the onset of metabolic syndrome; whereas a higher dose (100 mg/kg) shortens the mean lifespan likely due to renal failure." (PMID 33401592, 2021). "Speculatively, it has been suggested that smooth muscle proliferation, insulin, inflammation and metabolic syndrome may play central roles in pathogenesis of both BPH and heart disease." (PMID 34914804, 2021). "Furthermore, we have previously shown that transplantation of lean donor fecal microbiota can transiently improve insulin sensitivity in obese subjects with metabolic syndrome." (PMID 34177842, 2021). "Moreover, elevated ferritin levels have been found to be associated with other components of MetS including hypertension, dyslipidemia, elevated fasting insulin and blood glucose levels and central adiposity." (PMID 34209146, 2021). "Indeed, phenotype C PCOS patients manifest average values (compared with patients with other phenotypes of PCOS) of serum androgens, insulin, and testosterone, atherogenic lipids, hirsutism scores, and prevalence of metabolic syndrome." (PMID 33894770, 2021). "Moreover, this combination with insulin was administered to patients with co-morbidities, including hypertension, dyslipidemia, and coronary artery diseases." (PMID 33665047, 2021). "Therefore, enhancing insulin sensitivity is widely considered as an effective treatment strategy for metabolic syndrome." (PMID 34122092, 2021). "Moreover, it was shown that the risk of metabolic syndrome associated with TCF7L2 rs7903146 is augmented by dietary saturated fatty acid intake, with a further impairment of insulin sensitivity, which indicates that further analyses are required." (PMID 34200102, 2021). "By this process, under insulin-resistant circumstances, dyslipidemia may emerge, at least partly from mitochondrial dysfunction." (PMID 33804729, 2021). "Nonetheless, emerging pre-clinical data suggest that Δ9-THC leads to placental insufficiency, early cardiac deficits, dysglycemia (i.e., glucose intolerance, blunted insulin signaling) and dyslipidemia (i.e., augmented hepatic triglycerides, and visceral adiposity) in adult offspring." (PMID 34502436, 2021). "Therefore, the balance of CoQ10 levels plays a crucial role in seizure control as well as insulin-related metabolic syndrome in refractory seizure cases." (PMID 34574891, 2021). "Muscle, fat, and other tissues may become less sensitive to insulin as we age, resulting in dysglycemia and dyslipidemia." (PMID 34758878, 2021).
metabolic syndrome (continued). "The elevated plasma insulin levels may account for multiple metabolic syndrome features since insulin has been demonstrated to change glucose and lipid metabolism, enhance atherogenesis, and increase blood pressure." (PMID 34063474, 2021). "Likewise, it stands to reason that metabolic syndrome would have equally harmful effects on other insulin-sensitive tissues such as skeletal muscle." (PMID 33920751, 2021). "Therefore, the body will compensatively secrete excess insulin to maintain the stability of blood sugar, leading to hyperinsulinemia, which in turn leads to dyslipidemia." (PMID 34194325, 2021). "When honey was given along with insulin, the sensory nerve conduction improved, which might be due to the combined effect of reduction in glucotoxicity, dyslipidemia and rise in antioxidant level." (PMID 33449943, 2021). "Taken together, these findings indicate that KD exerts an enhancing effect on insulin sensitivity in high-fat diet-fed rats, which might be beneficial to the treatment of metabolic syndrome." (PMID 34122092, 2021). "The development of a manifold single pharmacological agent like tirzepatide that has the ability to significantly lower glucose levels, as well as improve insulin sensitivity, reduce weight and amend dyslipidemia at an early clinical stage is enormously important." (PMID 34819089, 2021). "As expected, insulin treatment in this model had beneficial effects on glucose control and dyslipidemia and increased body weight and fat mass, but also significantly improved liver histopathology by decreasing hepatic steatosis, inflammation and stellate cell activation." (PMID 33596938, 2021). "Furthermore, adolescents exposed to maternal psychosocial stress during intrauterine life consistently exhibit a higher BMI and body fat (%) with concomitant primary insulin resistance, and a lipid profile comparable to the metabolic syndrome." (PMID 33481865, 2021). "Additionally, it reversed insulin and glucose intolerance, dyslipidemia, adipocyte hypertrophy, and hepatic steatosis." (PMID 35011414, 2021). "After adjustment for age, sex, BMI, physical activity, smoking status, drinking status, γ-GGT, fasting insulin, eGFR, and ACR, the ORs and 95% Cis the associations of metabolic syndrome with low-grade albuminuria and CKD were 1.30 (1.05–1.61) and 1.71 (1.20–2.44), respectively." (PMID 33686966, 2021). "Such low prevalence of LVSD, asymptomatic of HF cohort, is unexpected given that 86.3% of our patients were overweight/pre-obese/obese, 83.1% had been diagnosed with T2DM for more than a decade (60.1% insulin requiring), 77.1% had hypertension, and 91.0% dyslipidemia." (PMID 34646868, 2021). "We cannot exclude the possibility that these discrepancies are due to additional factors that are present in the T2DM patients such as insulin levels, dyslipidemia and metabolic changes, medication, but they cannot be recapitulated in the in vitro system under high‐glucose conditions." (PMID 33942489, 2021). "Furthermore, cinnamon seems to be a possible source of NBCs for the prevention and treatment of IR and T2DM, activating PPARγ and PPARα, that induce an improvement in dyslipidemia and increases the insulin sensitivity." (PMID 33669163, 2021). "Moreover, quercetin treatment during pregnancy and lactation reduced adipose tissue mass, improved insulin resistance, and restored dyslipidemia programmed by maternal high-fat diet." (PMID 34769303, 2021). "In cardiac tissue, such hyperactivation of insulin/Akt signaling pathway has been described in other pathophysiological contexts, such as early stages of heart failure (i.e., pressure overload model) or metabolic syndrome (i.e., ob/ob mice)." (PMID 33682327, 2021).
metabolic syndrome (continued). "For the research of bibliography on PubMed and SciELO databases, a combination of the following medical subject headings (MeSH) was used: calorie restriction, fasting mimicking diets, fasting, ketogenic diet, metabolic syndrome, insulin resistance, healthy aging, performance." (PMID 33920973, 2021). "Based on our experimental data, deuterium-depleted water could be used to treat patients with metabolic syndrome (MS) by increasing insulin sensitivity." (PMID 34510301, 2021). "Chronic inflammation, oxidative stress, and excessive free fatty acid level in the blood caused by visceral fat accumulation have various adverse effects on the liver and muscle metabolism, including impaired insulin sensitivity, dyslipidemia, and liver cell apoptosis." (PMID 33935810, 2021). "Both hormones improve insulin sensitivity and glycemic control, and ameliorate dyslipidemia." (PMID 34065591, 2021). "Dysbiosis of gut microbiota may lead to the disruption in metabolism, such as dyslipidemia and insulin resistant." (PMID 34248898, 2021). "In addition, irisin appears to increase insulin sensitivity, promoting glucose transporter mobilization in insulin-dependent tissues, and improves metabolic syndrome and CVD." (PMID 33807959, 2021). "CA has been found to restore insulin signaling and dyslipidemia." (PMID 33204402, 2020). "The advantages and mechanism of PPAR-γ agonist includes inhibition of cytokine production by macrophages, reduction of oxidative stress, improving insulin resistance, control dyslipidemia due to the regulation of adipogenesis, and lowering blood pressure via vasodilation." (PMID 33172034, 2020). "Feeding rats on high-fructose (10% in drinking water) and high-salt diet (3%) for 12 weeks led to development of metabolic syndrome in these animals as indicated by the significant elevations in systolic blood pressure and serum insulin and increase in body weight." (PMID 32802123, 2020). "Indeed, arsenic can exert effects that are similar to the metabolic disturbances observed with increased visceral adiposity and metabolic syndrome, particularly insulin resistance in adipocytes." (PMID 33114645, 2020). "In insulin resistant states such as the metabolic syndrome, overproduction and impaired clearance of liver-derived very-low-density lipoproteins and gut-derived chylomicrons (CMs) contribute to hypertriglyceridemia and elevated atherogenic remnant lipoproteins." (PMID 32231641, 2020). "Skeletal muscle insulin response is one of the mayor processes altered in metabolic syndrome, thus leading to high plasmatic levels of glucose and insulin resistance." (PMID 32390830, 2020). "Although these mechanisms have not been elucidated, it is possible that metabolic factors other than insulin dysfunction may be involved in increased vasoconstriction, such as dyslipidemia, ROS and pro-inflammatory cytokines." (PMID 32187237, 2020). "Therefore, we further investigated if PT affects HFD-induced dyslipidemia by assessment of blood glucose, insulin and cholesterols." (PMID 33003300, 2020). "Understanding abnormal insulin signaling is an important goal because it can lead to a range of neurodegeneration, female infertility, kidney disease, blindness, stroke, cardiovascular disease, hypertension, and systemic disorders—dyslipidemia." (PMID 31936480, 2020). "Therefore, the improvement of dyslipidemia is beneficial for not only regulating insulin sensitivity but also controlling the occurrence and progression of diabetic complications." (PMID 33257645, 2020). "Therefore, our observation of a decreased ISSI-2 and unaltered HOMA-β reflects the impairment of glucose-stimulated insulin secretion and reservation of baseline insulin secretion, which is consistent with the metabolic syndrome." (PMID 32617139, 2020).
metabolic syndrome (continued). "Thus, poor diet contributes to the occurrence of a cluster of disorders known as the metabolic syndrome: abdominal obesity, hypertension, dyslipidemia, and disturbed metabolism of glucose or insulin." (PMID 32746858, 2020). "Furthermore, a lower prevalence of hypertension and dyslipidemia was noted in the insulin-sensitive group." (PMID 33116232, 2020). "In a pilot study, lean donor FMT into nine obese males with metabolic syndrome induced a small but significant improvement in peripheral insulin sensitivity and a trend toward improved hepatic insulin sensitivity when compared to participants that underwent autologous gut microbiota infusion." (PMID 33178196, 2020). "Thus, dysfunctional transport of FFA into adipocytes related to IR, as well as impaired suppression of breakdown of stored TG by insulin, contribute to the development of dyslipidemia and ectopic lipid deposition and tissue injury, characteristic of MUO." (PMID 32630256, 2020). "It has been found that intermittent fasting can prevent and reverse all aspects of metabolic syndrome in rodents: body fat, inflammation, and blood pressure are reduced; insulin sensitivity is increased; and the functional capacity of the neuromuscular and cardiovascular systems are improved." (PMID 32531935, 2020). "In addition, several clinical and basic research works have reported its potential use as an insulin sensitizer in different models of metabolic syndrome." (PMID 32390830, 2020). "However, the pharmacologic dyslipidemia therapies such as insulin and heparin were found to be insufficient to lowering TG rapidly." (PMID 32933540, 2020). "In sum, the p38 MAPK pathway is a double-edged sword that increases insulin-independent glucose uptake and mitochondrial oxidative phosphorylation in a healthy lifestyle while inhibiting, in unhealthy lifestyles, the same processes mediated by insulin signaling, leading to metabolic syndrome." (PMID 32899870, 2020). "These benefits were even more significant in the non-insulin users and patients with dyslipidemia." (PMID 33172034, 2020). "Besides, our review documented improvement in insulin sensitivity, anti-oxidative patterns, and dyslipidemia markers with co-supplementation of vitamin D and probiotics." (PMID 33396898, 2020). "In conclusion, exenatide inhibits atherosclerotic progression to delay the development of cardiovascular disease in patients with T2DM compared to insulin therapy, in addition to its benefits of glucose-lowering, body weight control, and dyslipidemia improvement." (PMID 32334592, 2020). "This study was later extended to humans, Kootte found at 6 weeks after lean donor (allogenic) fecal microbiota transplantation, insulin sensitivity of recipients with the metabolic syndrome was significantly improved, accompanied by altered microbiota composition." (PMID 32973686, 2020). "Overall, there is an apparent lack of hepatic abnormality in mice fed HFD for four weeks, whereas the insulin sensitivity is impaired, dyslipidemia is evident to some extent, and the kinetics of liver-derived proteins are altered, which leads to HDL remodeling." (PMID 33050482, 2020). "Thus, due to the positive effects of adiponectin on insulin sensitivity and metabolic syndrome, it seems that TG lowering agents can be used as therapeutic options in improving the insulin sensitivity of diabetic patients." (PMID 33680012, 2020). "It has been reported that relatively higher trunk fat levels were associated with various metabolic disturbances including worse glycemic control, elevated insulin levels, systemic inflammation, and dyslipidemia, which may accelerate the occurrence of CVD." (PMID 32342643, 2020). "However, all animals in the diabetic groups had elevated blood glucose and insulin levels and a phenotype consistent with a metabolic syndrome." (PMID 32587298, 2020).
metabolic syndrome (continued). "This inhibition of CPT1 may build up fatty acids and TGs accounting for higher lipogenesis and insulin resistance which might result in dyslipidemia." (PMID 32610503, 2020). "We could demonstrate that GMP, a milk-protein-derived peptide, is endowed with the potential to fight OxS, inflammation, intestinal lipoprotein production, and alterations of the insulin signaling pathways leading to postprandial dyslipidemia." (PMID 32331475, 2020). "The 16:1n-7 and 18:1n-9 MUFAS and 20:5(n-3) and 22:6(n-3) PUFAS are known to promote blood pressure control, adequate coagulation, enhanced endothelial function and preservation of insulin sensitivity, having beneficial effects on the prevention and treatment of metabolic syndrome." (PMID 32752280, 2020). "Acute CR improved glucose tolerance and reduced IRI in a model of metabolic syndrome likely through a reduction in hepatic gluconeogenesis, increased peripheral tissue glucose utilization induced via enhanced insulin sensitization, and increased NEFA uptake most likely by muscle." (PMID 32587574, 2020). "Patients in the lower HDL cholesterol tertile were younger, more frequently insulin-treated (31.4%), and showed increased values of BMI, triglycerides, uric acid, C-peptide, prevalence of metabolic syndrome and lower total cholesterol, statin (3.0%) and metformin (69.0%) treatment rates." (PMID 32375888, 2020). "Even though the literature on the simultaneous presence ofEW and AO in adolescents is scarce, health issues, such as cardiometabolic diseases, dyslipidemia, decreasedglucose tolerance, reduced insulin sensitivity, and early mortality, were directlyassociated with both conditions." (PMID 32401945, 2020). "Furthermore, muscle strengthening activities are closely related with improved insulin sensitivity, meliorated dyslipidemia, and reduced blood pressure, all of those are principle components of metabolic syndrome." (PMID 32365052, 2020). "An aggregate metabolic syndrome score for children was calculated using the z scores of waist circumference, systolic and diastolic blood pressures, and levels of triglyceride, high-density lipoprotein cholesterol, and insulin." (PMID 32176304, 2020). "Also, FMT from lean subjects to obese subjects with metabolic syndrome showed an increase in insulin sensitivity." (PMID 32047670, 2020). "However, in our study, patients with metabolic syndrome who consumed omega‐3 eggs had improved insulin levels by 14%, and this is statistically significant compared to other treatments." (PMID 32566179, 2020). "Some studies have reported that chromium picolinate is able to improve insulin sensitivity by reducing glucose and insulin levels in overweight or obese subjects, and to increase HDL cholesterol and decrease LDL levels, thus controlling metabolic syndrome risk factors." (PMID 32708059, 2020). "The better understanding on the interplay of these molecules in insulin-sensitive tissues might explore novel knowledge and provide treatment options to treat patients with metabolic syndrome." (PMID 33139672, 2020). "Regarding clinical efficacy in other applications of FMT, studies were too heterogeneous to perform meta-analyses, but four yielded evidence of clinical efficacy in slow-transit constipation, Hepatitis B, colonization of CPE, and insulin sensitivity in metabolic syndrome." (PMID 33345703, 2020). "Likewise, other authors have reported increased SFA plasma levels in aged individuals, with this fact being negatively related to insulin sensitivity and positively related to metabolic syndrome and arterial stiffness." (PMID 32503213, 2020). "Impaired lipid metabolism is common in insulin-resistant states, such as the metabolic syndrome." (PMID 32630214, 2020). "Thus, an improvement of insulin sensitivity in vulnerable subjects seems to be an adequate therapeutic approach for the treatment of metabolic syndrome." (PMID 32098371, 2020).